IL6 (interleukin 6)
Description:
Cytokine with a wide variety of biological functions in immunity, tissue regeneration, and metabolism. Binds to IL6R, then the complex associates to the signaling subunit IL6ST/gp130 to trigger the intracellular IL6-signaling pathway (Probable). The interaction with the membrane-bound IL6R and IL6ST stimulates 'classic signaling', whereas the binding of IL6 and soluble IL6R to IL6ST stimulates 'trans-signaling'. Alternatively, 'cluster signaling' occurs when membrane-bound IL6:IL6R complexes on transmitter cells activate IL6ST receptors on neighboring receiver cells (Probable). IL6 is a potent inducer of the acute phase response. Rapid production of IL6 contributes to host defense during infection and tissue injury, but excessive IL6 synthesis is involved in disease pathology. In the innate immune response, is synthesized by myeloid cells, such as macrophages and dendritic cells, upon recognition of pathogens through toll-like receptors (TLRs) at the site of infection or tissue injury (Probable). In the adaptive immune response, is required for the differentiation of B cells into immunoglobulin-secreting cells. Plays a major role in the differentiation of CD4(+) T cell subsets. Essential factor for the development of T follicular helper (Tfh) cells that are required for the induction of germinal-center formation. Required to drive naive CD4(+) T cells to the Th17 lineage. Also required for proliferation of myeloma cells and the survival of plasmablast cells (By similarity). Acts as an essential factor in bone homeostasis and on vessels directly or indirectly by induction of VEGF, resulting in increased angiogenesis activity and vascular permeability. Induces, through 'trans-signaling' and synergistically with IL1B and TNF, the production of VEGF. Involved in metabolic controls, is discharged into the bloodstream after muscle contraction increasing lipolysis and improving insulin resistance. 'Trans-signaling' in central nervous system also regulates energy and glucose homeostasis (By similarity). Mediates, through GLP-1, crosstalk between insulin-sensitive tissues, intestinal L cells and pancreatic islets to adapt to changes in insulin demand (By similarity). Also acts as a myokine (Probable). Plays a protective role during liver injury, being required for maintenance of tissue regeneration (By similarity). Also has a pivotal role in iron metabolism by regulating HAMP/hepcidin expression upon inflammation or bacterial infection. Through activation of IL6ST-YAP-NOTCH pathway, induces inflammation-induced epithelial regeneration (By similarity).
Synonyms: IL-6; BSF-2; CDF; IFN-beta-2; IFNB2; BSF2; HGF; HSF
Tractability: Small molecule: a structure with a bound ligand is known; a high-quality ligand is known; it has a binding pocket of medium quality. Antibody: an approved drug acts on it; UniProt places it where antibodies can reach, with high confidence; its Gene Ontology location is reachable by antibodies, with high confidence; UniProt predicts a signal peptide or a membrane-spanning region. PROTAC: ubiquitination databases record sites on it; a small molecule that binds it is known.
Target class: Secreted protein
Safety:
Unwanted effects reported when the protein is acted on. In parentheses: how it was acted on, where the effect was seen, and who reports it.
depression (source: ClinPGx)
Gene: Protein-coding gene on chromosome 7 (22,725,884 to 22,732,002, forward strand). Ensembl gene ENSG00000136244.
Subcellular location: Secreted
Subcellular location (Human Protein Atlas): Vesicles; Predicted to be secreted
Pathways (Reactome):
Immune System: Interleukin-10 signaling; Interleukin-4 and Interleukin-13 signaling; Interleukin-6 signaling
Disease: ADORA2B mediated anti-inflammatory cytokines production; CD163 mediating an anti-inflammatory response
Metabolism of proteins: Post-translational protein phosphorylation; Regulation of Insulin-like Growth Factor (IGF) transport and uptake by Insulin-like Growth Factor Binding Proteins (IGFBPs)
Signal Transduction: MAPK1 (ERK2) activation; MAPK3 (ERK1) activation
Cell-Cell communication: Activation of STAT3 by cadherin engagement
Cellular responses to stimuli: Senescence-Associated Secretory Phenotype (SASP)
Gene expression (Transcription): Transcriptional Regulation by VENTX
Gene Ontology:
Molecular function: cytokine activity; growth factor activity; identical protein binding; interleukin-6 receptor binding; protein binding
Biological process: cell surface receptor signaling pathway via JAK-STAT; cell surface receptor signaling pathway via STAT; cellular response to hydrogen peroxide; cellular response to lipopolysaccharide; cytokine-mediated signaling pathway; defense response to virus; glucose homeostasis; hepatic immune response; inflammatory response; inflammatory response to wounding; interleukin-6-mediated signaling pathway; negative regulation of apoptotic process; negative regulation of collagen biosynthetic process; negative regulation of primary miRNA processing; neuron projection development; neutrophil apoptotic process; positive regulation of acute inflammatory response; positive regulation of apoptotic DNA fragmentation; positive regulation of apoptotic process; positive regulation of B cell activation; positive regulation of cell population proliferation; positive regulation of chemokine production; positive regulation of cytokine production involved in inflammatory response; positive regulation of DNA-templated transcription; positive regulation of epithelial to mesenchymal transition; and 72 more
Cellular component: extracellular region; interleukin-6 receptor complex; endoplasmic reticulum lumen; plasma membrane
Genetic constraint (gnomAD): Loss-of-function variants: 6 observed, 13.43 expected, observed/expected ratio (o/e) 0.45, 90% interval 0.24 to 0.88. The upper end of that interval is the gene's LOEUF score, 0.88, which puts it in group 3 of 6, group 1 being the genes least tolerant of losing a copy. Missense variants: 217 observed, 207.44 expected, observed/expected ratio (o/e) 1.05, 90% interval 0.94 to 1.17. Synonymous variants: 82 observed, 81.38 expected, observed/expected ratio (o/e) 1.01, 90% interval 0.84 to 1.21.
Homologues: Orthologues: chimpanzee IL6 (98% identical), macaque IL6 (95% identical), dog IL6 (60% identical), pig IL6 (59% identical), rabbit IL6 (47% identical), mouse Il6 (42% identical), rat Il6 (41% identical), tropical clawed frog il6 (33% identical).
Diseases named in the same sentence as IL6 in open-access papers:
IL6 is named in the same sentence as 2,175 diseases in open-access papers, as found by Europe PMC text mining. Sharing a sentence is not in itself a finding about the gene and the disease. The quoted sentences say what the papers report.
COVID-19 (5,840 papers, 2020 to 2026). A disease caused by infection with severe acute respiratory syndrome coronavirus 2. "It has been reported that IL-6, IL-8, and IL-10 are associated with systemic inflammation and are increased in patients with COVID-19-related ARDS." (PMID 36817433, 2023). "The multivariate ordinal logistic analysis after adjusting for gender, vaccination date, and vaccination dose indicated that CRP at Days 4−7 and 8−14, IL‐6 on Days 4−7, and total antibody were risk factors for coronavirus disease 2019 severity." (PMID 35759224, 2022). "Overexpression of IL-6 can cause chronic inflammatory disorders and potentially fatal hyperinflammation, as seen in advanced coronavirus disease 2019 (COVID-19)." (PMID 35368692, 2022). "These authors described an early stage characterized by a viral response (SARS-CoV-2 viremia) and a final stage caused by a hyperinflammatory state characterized by increased levels of IL6." (PMID 35783606, 2022). "In vitro SARS-CoV-1 and CoV-2 infection of DCs and macrophages causes an increase of proinflammatory cytokines (IL-6, IL-8, MCP-1, MIP-1, TNF-α) and a decrease in IFN response and IL-12p40." (PMID 33557330, 2021). "These proangiogenic IL-6 properties have recently been brought into sharp focus in light of the central role inflammatory cytokines play in the devastating vasculopathy associated with severe acute respiratory syndrome coronavirus 2 (SARS-CoV-2) infection." (PMID 35318338, 2022). "The importance of RES is also due to its role as an anti-inflammatory agent since it promotes autophagy and inhibits the expression of pro-inflammatory agents, such as IL-6, IL-1β and IL-8 interleukins, decreasing the inflammatory process caused bySARS-CoV-2 infection." (PMID 35458574, 2022). "Immunomodulation may influence cytokine release syndrome: In this context, an elevated serum concentration of interleukin-6 was observed and was associated with higher levels of SARS-CoV-2 viremia, progression to mechanical ventilation, and death." (PMID 33540733, 2021). "Higher concentrations of IL-6 in serum are associated with higher levels of SARS-CoV-2 viremia." (PMID 35011848, 2021). "IL-6 demonstrated consistently high diagnostic performance in distinguishing individuals after COVID-19 from healthy controls (AUC > 0.82)." (PMID 42278658, 2026). "Genotyping was conducted for the two functional SNPs in the IL6 promoter region, rs1800796 and rs1800797, via Sanger sequencing, and for associations with COVID-19 susceptibility and IL-6 levels were analyzed." (PMID 41745088, 2026). "CONCLUSIONS: IL-6, IL-8, and IL-17 are identified as independent risk factors for the severity of COVID-19." (PMID 41580623, 2026). "Interleukin-6 (IL-6), a key pro-inflammatory cytokine, plays a crucial role in the immune response and has been strongly implicated in the pathogenesis of COVID-19." (PMID 41745088, 2026). "Multivariate logistic regression confirmed that IL-6, IL-8, and IL-17 were independent risk factors for COVID-19 severity." (PMID 41580623, 2026). "Co-infection also triggered robust increases in IFN-γ and IL-1β, whereas malaria alone was associated with higher IL-6, IL-4, and IL-10, and COVID-19 alone was associated with elevated IL-2 and TNF-α." (PMID 41758897, 2026). "This study aimed to assess the association between serum IL-6 levels and disease severity among hospitalized COVID-19 patients at Bangabandhu Sheikh Mujib Medical University (BSMMU)." (PMID 41773135, 2026). "This study aimed to evaluate the relationship between promoter region IL6 gene polymorphisms and COVID-19 susceptibility, as well as the inflammatory response, in pregnant women." (PMID 41745088, 2026). "Biomarkers of inflammation such as IL-6, ferritin, and D-dimer have been consistently linked to COVID-19 severity, suggesting an interaction between genetic predisposition and immune dysregulation." (PMID 40733568, 2025).
COVID-19 (continued). "IL-6 has been implicated in myocardial injury in patients with COVID-19, and IL-1 plays an important role in the inflammation of endothelial cells in coronary arteries." (PMID 41441313, 2025). "Studies have associated long COVID-19 with interleukin-1β, interleukin-6, and TNF (tumor necrosis factor)-alpha, along with chronic activation of a subset of CD8+ T cells—often called cytotoxic T lymphocytes." (PMID 40259977, 2025). "The consistent association of elevated IL-6, IL-10, and S100B levels with severe disease outcomes points to their potential use in stratifying COVID-19 patients based on risk." (PMID 41585373, 2025). "In fact, both meta-analyses and systematic literature reviews have confirmed the association between significantly elevated IL-6 levels and adverse clinical outcomes in COVID-19 patients." (PMID 40559430, 2025). "Monoclonal antibodies like TCZ are particularly suitable for managing severe inflammatory responses associated with COVID-19, such as elevated IL-6 levels." (PMID 40264651, 2025). "Consistent with previous studies, we found that both CRP and IL-6 were associated with worse outcomes from COVID-19 including mortality and requirement for 10-day intubation." (PMID 39969178, 2025). "In turn, HHV reactivations were more likely in individuals undergoing systemic steroid therapies for concomitant COVID-19 and were generally associated with increased serum IL-6 levels." (PMID 40572110, 2025). "We have shown that specific cytokine signatures reflect eGC damage and that interleukin 6 (IL-6) plays a causal role in glycocalyx damage in both patients with coronavirus disease 2019 (COVID-19) and those with bacterial sepsis." (PMID 40486505, 2025). "The dysregulation of cytokines, including TNF-α, IL-1β, and IL-6, can lead to a cytokine storm, contributing to the pathophysiology of COVID-19 and potentially causing severe inflammation and poor outcomes." (PMID 40909033, 2025). "In pancreatic cancer cells, all statins significantly downregulated the IL-6 gene encoding one of the major cytokines associated with COVID-19." (PMID 40722786, 2025). "Elevated IL-6 is linked to acute COVID-19 symptoms, including complement cascade upregulation, and current COVID-19 treatment regimens include the use of the IL-6 specific monoclonal antibody Tocilizumab." (PMID 39949890, 2025). "According to several research, an increase in IL-6 is the primary pathogenic factor in COVID-19-related heart rate to repair the QT interval prolongation." (PMID 40438117, 2025). "Higher IL-6 serum concentrations (p=0.03) were associated with more severe COVID-19, and higher serum IL-10 concentrations, (p=0.03) with mortality." (PMID 40352457, 2025). "These clinical observations are consistent with our findings and highlight the potential contribution of IL-6–mediated inflammation to COVID-19 mRNA vaccine-associated myocarditis." (PMID 41200189, 2025). "On the other hand, a study has shown that the risk of respiratory failure for patients with COVID-19 with IL-6 levels > 80 pg/mL was 22 times higher compared to patients with lower IL-6 levels." (PMID 40002608, 2025). "While the causal role of IL-6 in COVID-19 severity remains under investigation, it has been proposed as a potential biomarker for early disease detection and progression monitoring." (PMID 40406515, 2025). "COVID-19 is also associated with high levels of proinflammatory cytokines such as interleukin-6 (IL-6), IL-1B, IL-18, and granulocyte-macrophage colony-stimulating factor, a state commonly referred to as “cytokine storm”." (PMID 40066309, 2025). "Inflammatory cytokines, particularly IL-1 and IL-6, have frequently been implicated in the severe pulmonary form of COVID-19, especially during the cytokine storm." (PMID 40599143, 2025).
COVID-19 (continued). "Previous studies have shown that elevated fibrinogen levels in COVID-19 patients are significantly associated with increases in inflammatory markers such as interleukin-6, C-reactive protein, ferritin, erythrocyte sedimentation rate, and procalcitonin." (PMID 40791995, 2025). "In particular, IL-6 has emerged as a candidate biomarker because of its central role in COVID-19 pathophysiology, its strong association with disease severity, and its use for risk stratification and eligibility for IL-6–targeted drugs." (PMID 41517263, 2025). "A binary logistic regression analysis model showed that pneumonia caused by COVID-19 was associated with levels of IL-6 > 16 pg/ml (OR = 4.02; p < 0.01; 95% CI = 1.43–11.34) and IL-10 > 3 pg/ml (OR = 9.36; p < 0.01; 95% CI = 3.21–21.44)." (PMID 40508859, 2025). "Our threshold-free modelling suggests clinicians should consider early IL-6 quantification to triage high-risk patients, a strategy increasingly commonplace in COVID-19 management." (PMID 40872832, 2025). "In severe COVID-19 cases, the inflammatory response can cause significant damage, particularly to the lungs and heart, with cytokine levels such as IL-6 elevated significantly in more severe cases." (PMID 40584095, 2025). "Observational studies indicate that autoimmune patients on anti–TNF-α therapy have reduced severe COVID-19 incidence, aligning with our findings linking IL-6 and TNF-α to infection susceptibility in SLE." (PMID 40643149, 2025). "Monocytes, particularly the CD14+CD16+ subset, are linked to severe COVID-19 due to their production of pro-inflammatory cytokines like IL-6 and TNF-α, which can contribute to cytokine storm and tissue damage." (PMID 40370439, 2025). "The administration of calcifediol associated with corticosteroids in patients with COVID-19 significantly reduced circulating IL-6 (unpublished personal observation)." (PMID 40573079, 2025). "Elevated levels of inflammatory cytokines such as interleukin-6 (IL-6) and tumor necrosis factor-alpha are common in severe COVID-19 and are associated with increased thrombotic risk." (PMID 40110334, 2025). "In COVID-19, cytokines play a crucial role in the inflammatory response, with elevated levels of interleukin (IL)-6 being associated with disease severity and prognosis." (PMID 40909033, 2025). "Elevated levels of cytokines such as IL-6, IL-8, and TNFα have been linked to severe COVID-19 and the cytokine storm phenomenon, leading to ARDS and multi-organ failure." (PMID 40557167, 2025). "IL-6 plays a key role in the cytokine storm associated with COVID-19, as pro-inflammatory monocyte-derived macrophages contribute to lung injury by secreting high levels of this cytokine." (PMID 40661964, 2025). "A reverse assessment in a case–control study of COVID-19 showed increased salivary IL-6 measured at two time points in individuals with both COVID-19 and periodontitis, while periodontitis was associated with elevated salivary levels of RANKL and IL-1β." (PMID 41463036, 2025). "This was consistent with previous reports that higher IL-6 was associated with post-COVID-19 pulmonary fibrosis and IPF." (PMID 40472047, 2025). "Among biomarkers linked to disease severity in elderly COVID-19 patients, interleukin-6 (IL-6)—a pro-inflammatory cytokine—plays a key role and has also been associated with the progression of frailty." (PMID 41020118, 2025). "Elevated inflammatory markers (C-reactive protein (CRP), interleukin-6 (IL-6)) and clinical deterioration supported the diagnosis of COVID-19-associated myocarditis." (PMID 41322858, 2025). "Some of these cytokines such as IL18 (asthma, COPD) and IL6 (COVID-19) are implicated in serious lung diseases." (PMID 41292845, 2025). "Immune responses associated with COVID-19 exhibit dynamic and time-dependent alterations in the systemic levels of many cytokines, including IL-6, the kinetics of which are not fully understood, and thus, our mapping of this process is still incomplete." (PMID 39763770, 2025).